IGF1 (insulin like growth factor 1)
Diseases named in the same sentence as IGF1 in open-access papers (continued):
Sharing a sentence is not in itself a finding about the gene and the disease.
hypothyroidism (84 papers, 2009 to 2026). Abnormally low levels of thyroid hormone. "Thyroid hormones are crucial for normal growth and skeletal maturation, and hypothyroidism in children causes growth failure through delayed ossification and mineralization, decline in GHs and insulin-like growth factor 1, and impaired protein synthesis." (PMID 39981087, 2025). "Conversely, maternal hypothyroidism is associated with reduced IGF-1 levels at the maternal–fetal interface, a factor closely linked to IUGR." (PMID 40284249, 2025). "Two mediation effects were observed for insulin-like growth factor 1 on the associations for hypothyroidism (P for ACME <0.001) and Celiac disease (P for ACME <0.001)." (PMID 36842216, 2023). "Lastly, hypothyroidism has been associated with a reduction of insulin-like growth factor 1 (IGF1 and vascular endothelial growth factor (VEGF)." (PMID 32000713, 2020). "Furthermore, hypothyroidism exacerbates eGFR decline by reducing cardiac output, increasing peripheral vascular resistance, causing intrarenal vasoconstriction, and impeding the renal response to vasodilators such as vascular endothelial growth factor and insulin-like growth factor-1." (PMID 39981326, 2025). "Endocrinopathies included low IGF-1 levels (33.9%), subclinical/secondary hypothyroidism (32.2%), and secondary hypogonadism (21.4%)." (PMID 37775530, 2023). "Many of these effects are attributed to low insulin-like growth factor-1(IGF-1), hypogonadism, untreated secondary hypothyroidism, and glucocorticoid (GC) overuse." (PMID 36742387, 2023). "For instance, a loss of Grf1 or Dlk1 resulted in reduced GH content and secretion, while disruption of the imprinting domain encompassing Dlk1, Rtl1, and Dio3 resulted in transient perturbation in the GH/IGF-1 growth pathway with hypothyroidism." (PMID 35025875, 2022). "Free T4 (FT4) and free T3 (FT3) exert a permissive impact on IGF-1 action; it was demonstrated that hypothyroidism, even in its subclinical form, affected IGF-1 secretion." (PMID 34445772, 2021). "Patients with hypothyroidism were thinner (p=0.004) and more likely to be females (p=0.012), had larger and more invasive tumors, and lower levels of IGF-1 (p<0.001), compared to patients with normal thyroid function." (PMID 35154007, 2021). "Hyperprolactinemia (27/28, 96%), decreased IGF-1 level (12/16, 75%), and hypothyroidism (18/30, 60%) were also common." (PMID 30584530, 2018). "When the subjects who were diagnosed with hypothyroidism were evaluated as a separate group, a positive correlation was found between the age and the level of serum IGF-1." (PMID 29081797, 2017). "A strong positive correlation was observed between age and intranodular IGF-1 level (r = 0.77, p = 0.006) and serum IGF-1 levels (r = 0.67, p = 0.023) in the hypothyroidism group." (PMID 29081797, 2017). "We observed three key phenotypes in these mice: (i) embryonic growth retardation associated with altered expression of IGF1 binding proteins, (ii) peri-natal failure to thrive accompanied by hypothyroidism and low serum IGF1." (PMID 24034272, 2014). "The physiological functions of the ghrelin/GHS-R axis, namely stimulating GH release and increasing food intake, are interrupted, while the GH/IGF-1 axis operates independently from hypothyroidism." (PMID 25079659, 2014). "Insulin-like growth factor 1 (IGF-1) was low for her age, consistent with the well-established phenomenon of decreased growth hormone secretion in severe hypothyroidism." (PMID 23725039, 2013). "Following additional adjustments for growth hormone levels, insulin-like growth factor 1 levels, presence of hypothyroidism, physical activity and snoring, all four multivariable methods continued to support the causal relationship between childhood body and mandibular retrognathia." (PMID 40377818, 2025).
hypothyroidism (continued). "However, the association between childhood body size and mandibular retrognathia remained significant even after adjusting for growth hormone levels, insulin-like growth factor 1 levels, presence of hypothyroidism, physical activity and snoring." (PMID 40377818, 2025). "There were modest or weak but statistically significant correlations between LVEF and heart chamber volumes and IGF-1 serum concentration, suggesting that echocardiographic changes could relate to somatotropic insufficiency and secondary hypothyroidism." (PMID 38892756, 2024). "TED includes hypogonadism (hypoGn), anomalies of GH/IGF1 axes with growth retardation, hypothyroidism (hypoT), hypoparathyroidism (hypoPT), glucose profile anomalies, adrenal insufficiency, reduced bone mineral density (BMD), and deterioration of microarchitecture with increased fracture risk (FR)." (PMID 36010271, 2022). "In the affected KBDs included in the current study, low serum IGF-1 value had been measured in one dog (case 4), whereas one dog was diagnosed with hypothyroidism (case 2), and one was reported to have normal thyroid hormone values at the age of 13 weeks (case 1)." (PMID 33550451, 2021). "Conversely, abnormal GH and IGF-1 secretion occur in hypothyroidism." (PMID 31817511, 2019). "It was considered that a rise of IGF-1 level took place with aging in patients with hypothyroidism." (PMID 29081797, 2017). "However, the groups of the study subjects based on the results of thyroid function tests revealed that only the subjects with hypothyroidism had a positive correlation between age and serum IGF-1 level (r = 0.67, p = 0.023)." (PMID 29081797, 2017). "Hypothyroidism resolved, L-thyroxine was discontinued and IGF1 levels normalized." (PMID 25260871, 2014). "In cases of hypothyroidism co-occurring with IUGR, reductions in IGF-1 levels are especially pronounced, exacerbating growth limitations." (PMID 40284249, 2025). "In chickens, the treatment with propylthiouracil leads to hypothyroidism (T4 and T3 low) and this leads to lower GHR and IGF-1 mRNA expression in the liver." (PMID 35782551, 2022). "Two adult heterozygotes had mildly elevated IGF‐1 concentrations (Cases 1d and 2a) and one hemizygote (Case 1a) exhibited acromegaloid facies with inappropriately preserved IGF‐1 given his hypothyroidism." (PMID 30086211, 2018). "The present work reporting a lack of effect of hypothyroidism on IGF1 expression is consistent with prior work in swine in which late gestation fetal hypothyroidism resulted in no alterations in circulating IGF1 levels." (PMID 40693299, 2025). "Features previously discovered to have a role in bone metabolism include serum ferritin, type of iron chelator, zinc levels, levels of insulin-like growth factor-1 (IGF-1), hypothyroidism and calcium levels, physical activity and high caloric intake measured indirectly by body mass index (BMI)." (PMID 38978629, 2024). "According to our best knowledge, there is no data suggesting a correlation between age and serum IGF-1 levels in hypothyroidism and nodular thyroid disease." (PMID 29081797, 2017). "Our work provides an additional example of hypothyroidism, low IGF1 and growth retardation, which is not GH dependent, and highlights need for further research into TH pathway regulation of IGF1." (PMID 24034272, 2014). "Similarly, growth factors such as PDGF-A (p < 0.001), TGF-b, and IGF1 (p < 0.05) were transiently upregulated under non-physiological T3 conditions, especially hypothyroidism." (PMID 41718113, 2026). "The negative effects of hypogonadism on somatotropic-liver axis were also evident in the present work performed in male hypothyroid rats, where the orchiectomy reduced body weight growth, circulating IGF-I or hepatic Igf-1 mRNA levels to greater extent than hypothyroidism without castration." (PMID 38144555, 2023).
hypothyroidism (continued). "Expression of the major IGF ligands, IGF1 and IGF2, was not altered by MMI‐induced hypothyroidism, but six out of seven of the assessed IGFBPs were temporally dysregulated in the hypothyroid fetal LVR, with two of the IGFBPs temporally dysregulated in the fetal KID." (PMID 40693299, 2025).
liver fibrosis (84 papers, 2006 to 2026). "While the evidence is limited, previous case-control studies have demonstrated associations between severe forms of disease–hepatic fibrosis or hepatosplenic schistosomiasis–and decreased IGF-1 concentrations compared to control groups." (PMID 36197916, 2022). "GH-dependent Igf1 is an important protective mechanism against fibrosis, since hepatic fibrosis is accelerated in Igf-deficient cholestatic mice, but attenuated following Igf1 replacement." (PMID 27936029, 2016). "Consistent with our hypothesis, we observed that chronic HCV was associated with lower IGF-1 levels, with the strongest association observed among participants with advanced hepatic fibrosis/cirrhosis." (PMID 40700400, 2025). "Median and mean log levels of cytokines and insulin-like growth factor-1 according to liver fibrosis stage among those with chronic hepatitis C virus infection." (PMID 40700400, 2025). "Among participants with chronic HCV, mean log IL-6 was higher in magnitude among those with advanced hepatic fibrosis/cirrhosis, while mean log IGF-1 was lower in magnitude, compared to participants with chronic HCV who had no/minimal hepatic fibrosis." (PMID 40700400, 2025). "Liver fibrosis and cirrhosis development are often accompanied by GH resistance and low IGF-1 levels." (PMID 39910442, 2025). "Conversely, Insulin-like growth factor-1 (IGF-1) is proposed to protect against hepatic fibrosis through several mechanisms." (PMID 40777228, 2025). "Although this study revealed the potential mechanisms of BPA-induced MASLD and provided an in-depth exploration of the crucial roles of the PI3K/AKT signaling pathway, COL1A1, COL1A2, and IGF1 in hepatic fibrosis, several limitations remain." (PMID 41306725, 2025). "During hepatic fibrogenesis, IGF1 promotes the activation of hepatic stellate cells (HSCs) and their transformation into a fibroblastic phenotype through this pathway, driving liver fibrosis progression." (PMID 41306725, 2025). "Despite all these findings, the heterogeneity of disease’s pathogenesis through metabolic pathways underlines the need for deeper investigation, especially genetic factors such as IGF-1 and their penetration in disease progression and liver fibrosis." (PMID 39781288, 2025). "Studies on liver fibrosis have revealed the core role of the IGF1/IGF1R signaling system in controlling the liver fibrosis process." (PMID 38846640, 2024). "The results suggest that IGF-1 and exercise reduced liver fibrosis possibly by reducing ERS, creating adaptive ER stress status, and improving protein folding." (PMID 38468961, 2024). "Taken together, based on the changes in liver homeostasis, function and structure due to impaired GH/IGF-1 axis, treatment with IGF-1 induces the senescence of the liver stellate cells and improves hepatic fibrosis." (PMID 36419770, 2022). "Specific to S. mansoni infection, children experiencing hepatic fibrosis or hepatosplenic schistosomiasis had significantly lower IGF-1 concentrations compared to uninfected children." (PMID 36197916, 2022). "Experimental studies show that treatment with IGF-1 is particularly beneficial in the reduction of liver fibrosis, although positive effects in hepatic steatosis and inflammation can also be seen." (PMID 35448486, 2022). "For example, AOPB and IGF-1 are biomarkers reflecting the grade of liver fibrosis in hepatic patients and their levels were both significantly decreased after treatment." (PMID 35720415, 2022). "From another perspective, IGF-1 was reported to induce senescence of hepatic stellate cells and inhibited the progression of hepatic fibrosis in nonalcoholic steatohepatitis and cirrhotic mouse models." (PMID 36010307, 2022).
liver fibrosis (continued). "Many other biological pathways, such as hepatic fibrosis, IGF-1 signaling, epithelial adherent junction, and tight junction, were enriched by spaceflight with significant P values, but zero Z-scores due to a lack of other relevant supporting evidence." (PMID 34179686, 2021). "In the present study, we found the augment of hepatocyte oxidation and premature aging, along with the decrease of plasm IGF-1 level in patients with liver fibrosis and CCl4-induced liver injury rat models." (PMID 31171766, 2019). "In NASH patients, a lower level of IGF-1 compared with healthy controls was shown, and this discrepancy coincided with a higher histological severity of liver fibrosis." (PMID 31540048, 2019). "Our present study aims to investigate the role of IGF-1 in hepatocyte premature senescence in liver fibrosis mediated by progerin." (PMID 31171766, 2019). "IGF1 increased type I collagen gene expression and its accumulation in HSCs, which promoted liver fibrosis in vivo." (PMID 29702590, 2018). "Liver fibrosis severity analysis showed that external administration of IGF-1 attenuated liver fibrosis." (PMID 26152281, 2015). "We found that individuals with high or intermediate probability of advanced liver fibrosis have lower circulating IGF-1 levels as compared with individuals at low probability of liver fibrosis." (PMID 24520400, 2014). "Three canonical pathways showed evidence of interactions between the cell types: Hepatic Fibrosis/Hepatic Stellate Cell Activation Pathway, the IGF-1 Signaling Pathway and the VEGF Signaling Pathway (worksheets M, and O, respectively)." (PMID 21829467, 2011). "In advanced liver fibrosis, the IGF1 axis is severely impaired mostly due to a reduced number of healthy IGF1 producing hepatocytes." (PMID 20163708, 2010). "In that case the inhibition of IGF1 signalling by IGFBP5 would impair the pathogenesis of liver fibrosis." (PMID 20163708, 2010). "Decreased serum Igf-1 levels provide a useful index of hepatocellular dysfunction and impaired nutritional status, and increased Hgf appears to limit liver fibrosis." (PMID 17118137, 2006). "HCV-induced hepatic fibrosis could also contribute to hepatic and systemic metabolic dysregulation through impaired production of insulin-like growth factor (IGF)-1 in the liver." (PMID 40700400, 2025). "Top 10 pathways at 17 months of age included pathways related to collagen (e.g. GP6 signaling pathway and hepatic fibrosis hepatic stellate cell activation), growth signaling (IGF-1 signaling, molecular mechanisms of cancer) and the neuromuscular junction (synaptogenesis signaling pathway)." (PMID 38265577, 2024). "Individuals with liver fibrosis exhibit higher plasma levels of inflammatory and haemostatic factors, hyperuricaemia, lower circulating insulin-like growth factor-1 levels, endothelial dysfunction, and biomarkers of oxidative stress that lead to poor outcomes such as cardiovascular disease." (PMID 37711740, 2023). "Nevertheless, after performing a binary logistic regression, the IGF-1/intact IGFBP-3 ratio did not remain robustly associated with NASH or liver fibrosis (p = 0.06 unadjusted and p = 0.08 after adjusting for BMI and age)." (PMID 36831184, 2023). "Finally, we confirmed that chromatograph isolation is a suitable method for the purification of engineered EVs, keeping their potential to carry IGF-1 and their in vivo therapeutic effect on liver fibrosis in mice." (PMID 37298538, 2023). "Furthermore, IGF-1-modified BMMSCs mitigated liver fibrosis in mice through downregulation of HSC activation." (PMID 36248254, 2022). "Furthermore, IGF-1 limits the activity of hepatic stellate cells and induces their senescence, therefore attenuating hepatic fibrosis." (PMID 35448486, 2022).
liver fibrosis (continued). "Multivariate regression was performed after the correlation study, showing that GH as well as IGF1 values, adjusted for Tanner’s stage, sex and BMI, were negatively associated with HOMA-IR but above all with liver fibrosis (GH:→β = −2.3, SE 0.31, p = 0.001; IGF1:→β = −2.8, SE = 1.1, p = 0.001)." (PMID 36557260, 2022). "Even though the molecular mechanisms linking IGF-1 and the progression of liver damage in the setting of NAFLD have not been elucidated yet, recent data describe a novel role of IGF-1 in regulating stress-induced hepatocyte premature senescence in liver fibrosis." (PMID 33800465, 2021). "Moreover, recombinant IGF-1 or the transfer of IGF from human umbilical cells ameliorates liver fibrosis, decreasing α-SMA and Masson’s trichomic stain, EMC." (PMID 34943914, 2021). "However, the underlying mechanisms about hepatocyte premature senility in liver fibrosis, and how IGF-1 regulates cell premature aging and fibrogenesis, remain poorly understood." (PMID 31171766, 2019). "Low IGF1, and IGF1/IGFBP3 ratio may be associated with advanced liver fibrosis, while low levels of GH might have a role in hepatic steatosis in NAFLD." (PMID 29702590, 2018). "In a multivariable linear regression model, progression of liver fibrosis was associated with HIV infection and age, as well as with a slower rate of IGF-1 decline (P = 0.001); however, the rate of IGF-1 decline did not alter the strength of the associations between HIV, liver disease, and age." (PMID 28503671, 2017). "However, the panorama of the mechanism of IGF-1 alleviating liver fibrosis still needs to be elucidated." (PMID 26152281, 2015). "The observed effects of IGFBP5 may therefore be due to its role in IGF1 signalling - that is to its disturbance of the IGF1 axis observed in liver fibrosis." (PMID 20163708, 2010). "The decrease in IGF1 signalling seems to provide a pro-fibrotic environment, since the progression of liver fibrosis could be delayed by IGF1 administration." (PMID 20163708, 2010). "IGF-I could directly inhibit the proliferation and activation of HSCs to improve the progression of hepatic fibrosis, and parasite-related experiments had reported that IGF-1 promotes parasitism and survival of parasites on hosts, and accelerated disease progression." (PMID 39436864, 2024). "In addition, the IGF-1/intact IGFBP3 ratio is reduced in patients with liver fibrosis." (PMID 35154570, 2022). "Several studies preliminarily suggested that growth hormone (GH) levels and insulin-like growth factor-1 (IGF-1) levels are negatively associated with NAFLD in adults, and GH replacement therapy in GH-deficient patients can alleviate NAFLD and improve liver fibrosis." (PMID 32209063, 2020). "Hence, progerin, a pivotal protein, was likely linked to oxidative stress-induced hepatocyte premature senility for facilitating liver fibrosis; and IGF-1 may influent progerin-related pathway to attenuate premature senescence and fibrosis." (PMID 31171766, 2019). "In addition, IGF-1 decline was independently associated with liver fibrosis progression, but this decline did not appear to explain how HIV infection “ages” the liver." (PMID 28503671, 2017). "Moreover, recent studies showed that IGF-1 replacement or gene transfer therapy induced cytoprotective and anti-inflammatory effects leading to improvement of hepatic fibrosis in cirrhotic rats, and IGF-1 treatment improved serum albumin levels in patients with cirrhosis." (PMID 24595361, 2014). "As compared with individuals at low probability of liver fibrosis, the individuals at intermediate probability of fibrosis exhibited an unfavorable cardio-metabolic risk profile having significantly higher values of waist circumference, hsCRP, fibrinogen, ESR, as well as lower levels of IGF-1." (PMID 25111713, 2014).